PRRG3 (proline rich and Gla domain 3)
Synonyms: PRGP3; TMG3
Tractability: Antibody: UniProt predicts a signal peptide or a membrane-spanning region; its Gene Ontology location is reachable by antibodies, with medium confidence.
Gene: Protein-coding gene on chromosome X (151,694,607 to 151,705,924, forward strand). Ensembl gene ENSG00000130032.
Subcellular location: Membrane
Gene Ontology:
Molecular function: serine-type endopeptidase activity; calcium ion binding
Biological process: blood coagulation; proteolysis
Cellular component: membrane; extracellular region
Homologues: Orthologues: chimpanzee PRRG3 (99% identical), macaque PRRG3 (97% identical), pig PRRG3 (96% identical), dog PRRG3 (94% identical), mouse Prrg3 (94% identical), rat Prrg3 (94% identical), guinea pig PRRG3 (93% identical), tropical clawed frog prrg3 (55% identical), zebrafish PRRG3 (52% identical). Paralogues in human: PRRG1 (34% identical), PRRG4 (20% identical), OVCH2 (11% identical).
Diseases named in the same sentence as PRRG3 in open-access papers:
PRRG3 is named in the same sentence as 3 diseases in open-access papers, as found by Europe PMC text mining. Sharing a sentence is not in itself a finding about the gene and the disease. The quoted sentences say what the papers report.
prostate carcinoma (1 paper, 2022). A carcinoma that arises from epithelial cells of the prostate gland. "High expression of PRRG3 is associated with increased risk of prostate cancer." (PMID 35875673, 2022).
cancer (2 papers, 2010 to 2020). A tumor composed of atypical neoplastic, often pleomorphic cells that invade other tissues. "PRRG3 is a protein-coding gene, but to the best of our knowledge, no research has explored its role in cancer." (PMID 33281882, 2020). "To date, none of the 6 other HRneg/Tneg signature genes not functionally linked to chemokine pathways (PRRG3, RFX7, MATN1, SSX3, HRBL, and ZNF3) has shown any reported association with cancer." (PMID 20946665, 2010).
PRRG3 also shares sentences with these, for which no sentence is quoted: breast carcinoma (1 paper).